UGT1A1 (UDP glucuronosyltransferase family 1 member A1)
Diseases named in the same sentence as UGT1A1 in open-access papers (continued):
Sharing a sentence is not in itself a finding about the gene and the disease.
thalassemia (2 papers, 2015 to 2025). An inherited blood disorder characterized by a decreased synthesis of one of the polypeptide chains that form hemoglobin. "The severity of SCD complications differ depending on variations in hemoglobin haplotype, HbF, α-thalassemia, Glucose-6-phosphate dehydrogenase deficiency, and UGT1A1 promoter polymorphisms." (PMID 39946434, 2025). "This study investigates the influence of UGT1A1 polymorphism, HbF level, βs haplotypes and α thalassaemia on the steady state bilirubinemia and propensity to develop gall stones in Omani SCA patients." (PMID 26543529, 2015).
angina (1 paper, 2021). "Among cardiovascular patients with angina or heart failure, the UGT1A1*6/*6 genotype had a lower capacity to glucuronidate the beta-blocker carvedilol compared with patients with the wild-type UGT1A1*1/*1 genotype." (PMID 34198586, 2021).
Anosmia (1 paper, 2024). An inability to perceive odors. "In cases of post-COVID anosmia, the observation that the UGT1A1 locus remains hypomethylated, which could suggest a potential role of epigenetic mechanisms." (PMID 39767184, 2024). "We selected UGT1A1 as a target because no SNP variants associated with anosmia have been identified in UGT1A1 and it is a homolog of UGT2A1 implicated in olfactory function." (PMID 39767184, 2024).
autoimmune hepatitis (1 paper, 2021). Hepatitis caused by autoantibodies. "The study also reports new findings on DMEs profile in autoimmune hepatitis, where only downregulation trend of the studied enzymes was documented (except for UGT1A1 and UGT1A3), but without reaching statistical significance (p > 0.05)." (PMID 34575411, 2021).
bilirubin encephalopathy (1 paper, 2022). "Thus, this study aimed to investigate the association between genetic variants of UGT1A1 and hyper-free bilirubinemia, which is more directly associated with the development of bilirubin encephalopathy than hyper-total bilirubinemia." (PMID 36293671, 2022). "Thus, the contribution of UGT1A1 genetic variants to kernicterus or bilirubin encephalopathy has not been elucidated." (PMID 36293671, 2022).
breast disease (1 paper, 2012). "This increase in UGT1A1 mRNA levels in more aggressive stage of breast disease could be attributed to epigenetic regulation of UGT1A1 resulting in variations in response to chemotherapy used for the treatment of more aggressive cancers." (PMID 30349745, 2012). "To further determine if UGT1A1 mRNA levels had an effect on clinicopathological and variable factors, we compared UGT1A1 mRNA expression levels to ethnicity, menopausal status, and stage of breast disease." (PMID 30349745, 2012). "Interestingly, UGT1A1 mRNA levels were slightly higher, but not significantly, in more aggressive and advanced stages of breast disease as compared to early stages of breast disease (Stage I/II: 0.3 ± 0.2; Stage III/IV: 0.5 ± 0.3, p = 0.56)." (PMID 30349745, 2012).
cervical cancer (1 paper, 2020). A primary or metastatic malignant neoplasm involving the cervix. "Irinotecan chemotherapy might be beneficial in patients with cervical cancer, UGT1A1 polymorphisms, and ≤ 1 metastatic lymph nodes." (PMID 32758288, 2020). "We aimed to determine whether UGT1A1 polymorphisms can predict progression-free survival in patients with local cervical cancer treated with irinotecan chemotherapy." (PMID 32758288, 2020). "This study implied that the UGT1A1 polymorphism might also stratify patients and act as a predictive prognostic factor for the efficacy of CPT-11/NDP in cervical cancer patients." (PMID 32758288, 2020). "Therefore, we determined the influence of UGT1A1 polymorphism on the prognosis, specifically progression-free survival (PFS), of local cervical cancer patients treated with CPT-11/NDP, including in patients at a high risk for recurrence." (PMID 32758288, 2020). "In conclusion, CPT-11/NDP might be beneficial in patients with cervical cancer, no or one metastatic lymph nodes, and UGT1A1 polymorphism." (PMID 32758288, 2020).
chronic hepatitis C (1 paper, 2022). "A case–control study has suggested that chronic hepatitis C patients with increased bilirubin levels have a high frequency of UGT1A1*28." (PMID 36128448, 2022).
developmental delay (1 paper, 2017). "When neonatal humanized UGT1 (hUGT1) mice, which exhibit severe levels of total serum bilirubin (TSB) because of a developmental delay in expression of the UGT1A1 gene, were treated with PEITC, TSB levels were reduced." (PMID 28422158, 2017).
diffuse large B-cell lymphoma (1 paper, 2022). "In contrast, an irinotecan‐containing chemotherapy regimen (carboplatin, dexamethasone, etoposide, and irinotecan [CDE‐11]) for adult diffuse large B‐cell lymphoma has been shown to improve prognosis in patients with the UGT1A1*6 polymorphism." (PMID 35233973, 2022).
Fabry disease (1 paper, 2017). Fabry disease (FD) is a progressive, inherited, multisystemic lysosomal storage disease characterized by specific neurological, cutaneous, renal, cardiovascular, cochleo-vestibular and cerebrovascular manifestations. "The aim of our study was to assess the possible relationships among heme oxygenase (HMOX), bilirubin UDP-glucuronosyl transferase (UGT1A1) promoter gene variations, serum bilirubin levels, and Fabry disease (FD)." (PMID 28951772, 2017).
Glucose intolerance (1 paper, 2025). Glucose intolerance (GI) can be defined as dysglycemia that comprises both prediabetes and diabetes. "The UGT1A1-RNAi lowered plasma urobilin levels, adiposity, glucose intolerance, hepatic lipid accumulation, and pro-inflammatory kinase signaling pathways, which suggests targeting UGT1A1 to control urobilin levels as a potential therapeutic." (PMID 40002715, 2025).
granulocytopenia (1 paper, 2020). "Clinical studies have shown that Caucasians with UGT1A1*28 gene mutants (TA6/7 and TA7/7) have a higher risk of severe granulocytopenia and diarrhea than those with wild-type UGT1A1*28 (TA6 /6) after receiving irinotecan." (PMID 32264830, 2020). "For the effect of UGT1A1* 28 mutant on delayed-onset diarrhea and 3~4 grade granulocytopenia, only one adverse reaction was mentioned in some studies." (PMID 32264830, 2020).
hemolysis (1 paper, 2026). Disruption of the integrity of the erythrocyte membrane causing release of hemoglobin. "Patients underwent ARMS-PCR genetic testing for the UGT1A1 c.-3279T > G variant.Patients with hemolysis or hepatobiliary disease were excluded." (PMID 41973709, 2026).
hereditary hemochromatosis (1 paper, 2023). An inherited metabolic disorder characterized by iron accumulation in the tissues. "As another example, UGT1A1*28, UGT1A1*60, and cytochrome P450 1A2 (CYP1A2) rs762551 were associated with a pazopanib-related increase in bilirubin, while SNPs in hereditary hemochromatosis gene (HFE) were associated with increased levels of ALT." (PMID 37370844, 2023).
laryngeal carcinoma (1 paper, 2016). Carcinoma that arises from the laryngeal epithelium. "In this study, we investigated the UGT1A1*6 polymorphism in patients with laryngeal cancer by means of HRM technique, as well as smoking or alcohol consumption in the occurrence of laryngeal cancer." (PMID 26751466, 2016). "In this study on the relation between the UGT1A1*6 polymorphism and the risk of laryngeal cancer, we found an association between the rs4148323 G allele and an increased risk of laryngeal cancer." (PMID 26751466, 2016). "Stratification analysis of the strength of the association between UGT1A1 rs4148323 and laryngeal cancer." (PMID 26751466, 2016). "The impact of UGT1A1*6 polymorphisms in relation to laryngeal cancer risk requires further validation in studies including larger samples." (PMID 26751466, 2016). "In conclusion, the rs4148323 G allele is associated with the high UGT1A1 enzyme activity, and might increase the risk of laryngeal cancer." (PMID 26751466, 2016). "In conclusion, the rs4148323 G allele is associated with the high UGT1A1 enzyme activity, and may increase the risk of laryngeal cancer." (PMID 26751466, 2016). "Since serum bilirubin concentrations are inversely correlated with UGT1A1 activity and the rs4148323 A allele is associated with decreased UGT1A1 activity, it can hypothesized that rs4148323 A allele might decrease individual risk of developing laryngeal cancer." (PMID 26751466, 2016). "The aim of this study was to examine UGT1A1*6 (rs4148323 A/G) polymorphisms in 103 patients with laryngeal cancer and 220 controls using the high resolution melting curve (HRM) technique and to explore the association between UGT1A1*6 (rs4148323 A/G) polymorphisms and laryngeal cancer." (PMID 26751466, 2016).
leprosy (1 paper, 2015). Leprosy is a chronic infectious disease affecting primarily the skin and peripheral nervous system. "We investigated the possible effects of CYP19A1 [rs11575899], NFKβ1 [rs28362491], IL1α [rs3783553], CASP8 [rs3834129], UGT1A1 [rs8175347], PAR1 [rs11267092], CYP2E1 [INDEL 96pb] and IL4 [rs79071878] genes in a group of 141 leprosy patients and 180 healthy individuals." (PMID 26367014, 2015).
metastatic disease (1 paper, 2018). "ESMO alone advises microsatellite instability testing in the setting of metastatic disease, and JSCCR is the only one to advise UDP‐glucuronosyltransferase1A1 (UGT1A1) phenotyping." (PMID 30511044, 2018).
mucinous carcinoma (1 paper, 2020). "UGT1A1*28 is associated with mucinous carcinoma and may have a role in the formation of specific histologic sub-groups." (PMID 31895688, 2020).
osteoarthritis (1 paper, 2022). A noninflammatory degenerative joint disease occurring chiefly in older persons, characterized by degeneration of the articular cartilage, hypertrophy of bone at the margins and changes in the synovial membrane. "In addition to changes in UGT1A1, polymorphisms in the transporter proteins SLCO1B1 and ABCB1 have been reported to influence the response of osteoarthritis patients to raloxifene treatment." (PMID 35453603, 2022).
pancreatic ductal adenocarcinoma (1 paper, 2023). An infiltrating adenocarcinoma that arises from the epithelial cells of the pancreas. "The effects of UGT1A1 gene polymorphisms or prior irinotecan treatment on treatment outcomes of nanoliposomal-irinotecan plus 5-fluorouracil/leucovorin (nal-IRI+5-FU/LV) in patients with unresectable pancreatic ductal adenocarcinoma (PDAC) are not established." (PMID 36836140, 2023).
pneumonitis (1 paper, 2026). An inflammatory process affecting the lung parenchyma. "Thus, trastuzumab‐deruxtecan may be a valid alternative in patients with reduced UGT1A1 function, but both its other adverse effects (for example pneumonitis) and cost would need to be considered." (PMID 40936312, 2026).
primary hyperoxaluria type 1 (1 paper, 2012). A rare disorder of glyoxylate metabolism characterized by the accumulation of oxalate due to a deficiency of the peroxisomal hepatic enzyme L-alanine: glyoxylate aminotransferase (AGT). "This leads to extensive repopulation of the liver with complete correction of the metabolic defect in the uridinediphosphoglucuronate glucuronosyltransferase 1A1 (ugt1a1)-deficient Gunn rat model of Crigler-Najjar syndrome type 1 (CN1) and a mouse model of primary hyperoxaluria type 1 (PH1)." (PMID 23091601, 2012).
prostate tumors (1 paper, 2010). "Recent studies from our laboratory and others have found that the expression levels of SOD, UGT1A1, NQO1 and several GST family genes were significantly suppressed in prostate tumors in Transgenic Adenocarcinoma of Mouse Prostate (TRAMP) mice." (PMID 20062804, 2010). "Similarly, the expression of Nrf2 as well as its downstream target genes such as UGT1A1, GSTM1 and NQO1 were found to be gradually down-regulated in prostate tumors with the progression of prostate tumorigenesis in TRAMP mice." (PMID 20062804, 2010).
renal cell cancer (1 paper, 2021). "Neither the UGT1A1 SNP nor the non-UGT1A1 SNPs were associated with risk of renal cell cancer in men and women combined; however, a suggestive inverse association was observed between bilirubin levels predicted by the non-UGT1A1 SNPs and renal cell cancer in men (OR 0.76; 95% CI 0.57–1.00)." (PMID 33671849, 2021).
Splenomegaly (1 paper, 2014). Abnormal increased size of the spleen. "In summary, our 16-year-old Chinese patient with hepatalgia, jaundice, hyperpigmentation, and splenomegaly was shown to be a heterozygous H63D and homozygous IVS 2 + 4 T → C HFE and heterozygous G71R UGT1A1 gene mutation patient with simultaneous HHC and GS manifestations." (PMID 25262004, 2014).
steatosis (1 paper, 2022). Increased lipid within the cytoplasm of cells. "Circulating TB levels were weakly associated with liver fat fraction in patients with NAFLD, and the circulating UGT1A1 levels were positively correlated with liver fat fraction in NAFLD patients with severe steatosis." (PMID 34986792, 2022). "When patients with NAFLD come out the increased serum TB and UGT1A1 levels, a severe steatosis of progression might be occurred, which can guide the clinical surveillance and treatment of patients with NAFLD." (PMID 34986792, 2022). "When the NAFLD patients were graded to mild, moderate, and severe steatosis by the MRI-PDFF values, the circulating UGT1A1 levels were positively correlated with liver fat fraction in patients with severe steatosis, which was consistent with the previous study." (PMID 34986792, 2022).
stomatitis (1 paper, 2018). Inflammation of the oral mucosa due to local or systemic factors. "In addition, we showed that taking into account both DPYD and UGT1A1 genotypes allows predicting with high specificity grade ≥ 3 hematological AEs, including febrile neutropenia, and stomatitis." (PMID 29487697, 2018).
T-Cell Acute Lymphoblastic Leukaemia (1 paper, 2025). "In this case report, a young child of Southeast Asian ethnicity with T-cell ALL, who demonstrated reversible non-haemolytic indirect hyperbilirubinemia during maintenance chemotherapy, was found to have a UGT1A1 polymorphism consistent with GS." (PMID 39996891, 2025).
tubular adenocarcinoma (1 paper, 2017). An infiltrating adenocarcinoma in which the malignant cells form tubular structures. "The genotype frequencies for the UGT1A1 polymorphism at position −211 were associated with the histological type, in which patients with GG genotype showed a predisposition to developing tubular adenocarcinoma." (PMID 28056823, 2017). "Additionally, patients carrying G allele at −211 of UGT1A1 were predisposed to developing tubular adenocarcinoma, while individuals carrying 6TAA or G allele respectively at *28 or −3156 of UGT1A1 tended to have a local invasion." (PMID 28056823, 2017).
Wilson disease (1 paper, 2021). A very rare inherited multisystemic disease presenting non-specific neurological, hepatic, psychiatric or osseo-muscular manifestations due to excessive copper deposition in the body. "It is worth to mention, that UGT1A1 protein abundance is decreased in Atp7b−/− mouse model of Wilson’s disease." (PMID 34117631, 2021).
cancer (87 papers, 2004 to 2025). A tumor composed of atypical neoplastic, often pleomorphic cells that invade other tissues. "The epidemiology and frequency of UGT1A1 genes polymorphisms by race, gender, ethnicity, geographic location and stage of the cancer were correlated with drug metabolism, toxicity, and survival outcomes." (PMID 40432911, 2025). "Several studies suggested that UGT1A1 glucuronidases cancer-causing compounds to make them water-soluble and excretable." (PMID 41031088, 2025). "By potentially altering the ability to metabolize and excrete carcinogens and chemotherapeutic drugs, UGT1A1 polymorphisms can influence both cancer risk and clinical outcomes in different cancer types." (PMID 37760555, 2023). "Data from Asian patients showed that cancer patients had a similar frequency of the UGT1A1*6 allele compared to normal individuals (16.7% vs. 13%), but those prevalence rates were lower than observed in Korean cancer patients." (PMID 36239106, 2022). "Several genetic variants in UGT1A1 have been associated with toxicity induced by irinotecan and by other cancer drugs." (PMID 36297516, 2022). "The seven TA-repeats allele of UGT1A1*28 polymorphism underlying GS was investigated in relation to cancers of the endometrium, ovary, lung, breast, and prostate." (PMID 33671849, 2021). "Fourth, although we applied several strategies to account for horizontal pleiotropy, we cannot test and exclude the possibility that the main UGT1A1 SNP affects cancer risk through pathways other than elevated bilirubin levels." (PMID 33671849, 2021). "For example, adverse drug reactions when patients receive CPT-11 (irinotecan) such as in cancer chemotherapy are caused by amino acid substitutions in UGT1A1." (PMID 31730632, 2019). "For example, optimal warfarin dosing is known to be dependent on variants in CYP2C9 in addition to VKORC1 and variants in the ADME gene UGT1A1 are documented to contribute to different responses to the cancer drug irinotecan around the globe." (PMID 29273096, 2017). "The present meta-analysis assessed the association of UGT1A1*28 polymorphisms with clinical outcomes of IRI-based chemotherapy in a single cancer site, CRC." (PMID 23516488, 2013). "FDA has guidelines about the anti-cancer drug Irinotecan, stating that reduction in the starting dose should be considered for patients known to be homozygous for the UGT1A1*28 allele." (PMID 19609385, 2008). "The routine mutational screening of the UGT1A1 gene in cancer patients remains a topic of debate." (PMID 39996891, 2025). "Chemicals that cause stomach lining cancer are broken down by UGT1A1." (PMID 41031088, 2025). "Therefore, the polymorphisms of the UGT1A1*28 gene were associated with the incidence of grade 3–4 diarrhea in cancer patients during IRI chemotherapy, and the incidence of wild-type (TA6/6) was lower." (PMID 40170723, 2025). "And UGT1A1 expression or activity may alter stomach lining cancer-causing material elimination and GC risk." (PMID 41031088, 2025). "UGT1A1*28 linked to increased toxicity of the anti-cancer drug irinotecan, is also well documented." (PMID 36266537, 2023). "Serum concentrations of bilirubin were inversely correlated with UGT1A1 activity, indicating that low activity might increase bilirubin levels, with a corresponding decrease in the risk of developing cancer." (PMID 26751466, 2016). "We therefore set out to determine whether specific tumor characteristics and the age of cancer onset were influenced by the SULT1A1 or UGT1A1 alleles." (PMID 16280036, 2005). "Therefore, the observed differential associations of the UGT1A1 SNP across cancer types may also reflect the modulated metabolism of such substances with carcinogenic potential." (PMID 33671849, 2021). "Mutations in UGT1A1-6 and UGT1A1-28 are associated with increased risk and severity of side effects in patients treated with IRI (CPT-11) for various cancers." (PMID 40432911, 2025).